GABRB3 (gamma-aminobutyric acid type A receptor subunit beta3)
Diseases named in the same sentence as GABRB3 in open-access papers (continued):
Sharing a sentence is not in itself a finding about the gene and the disease.
schizophrenia (6 papers, 2014 to 2022). A major psychotic disorder characterized by abnormalities in the perception or expression of reality. "The functional sequences of the GABRB3 gene regulatory region and subsequent effects on the GABRB3 receptor were further investigated to clarify the association between the receptor and schizophrenia." (PMID 30908890, 2019). "We show how prenatal loss of endothelial Gabrb3 can directly lead to abnormal increases in neocortical blood flow and contribute to dysfunction in several behavioral domains that have been linked with anxiety, depression, and schizophrenia." (PMID 35318369, 2022). "Our group previously identified an association between NG_012836.1:g.4160T>C and NG_012836.1:g.4326G>A in the 5′ regulatory region of the GABRB3 gene by Sanger sequencing and hypothesized that the C‐A haplotype may increase the risk of schizophrenia." (PMID 30908890, 2019). "This study investigated the effects of haplotypes T‐G and C‐A derived from NG_012836.1:g.4160T>C and NG_012836.1:g.4326G>A on protein expression levels in vitro and identified the functional sequence in the regulatory region of the GABRB3 gene linked to possible associations with schizophrenia." (PMID 30908890, 2019). "Furthermore, downregulation of GABRB3 may contribute to the pathophysiology and clinical manifestation of schizophrenia through altered oscillation synchronization in the superior temporal gyrus." (PMID 35562887, 2022). "Moreover, studying functional fragments of the GABRB3 gene regulatory region and the potential association with schizophrenia have not been specific enough." (PMID 30908890, 2019). "The CAMK1D, GABRB3, and RBFOX1 genes have been suggested to contribute to schizophrenia physiopathology." (PMID 30034349, 2018).
childhood absence epilepsy (5 papers, 2011 to 2023). A familial generalized pediatric epilepsy, characterized by very frequent (multiple per day) absence seizures, usually occurring in children between the ages of 4 and 10 years, with, in most cases, a good prognosis. "Previous studies reported that SNPs at the 5′ regulatory region of GABRB3 could regulate GABRB3 gene expression and associated with childhood absence epilepsy (CAE)." (PMID 25025424, 2014). "Missense or nonsense mutations of GABRA1, GABRB3, and GABRG2 are linked with GEFS+, childhood absence epilepsy, febrile seizures, and juvenile myoclonic epilepsy." (PMID 38003469, 2023). "Rare genetic missense mutations of GABRB3 have been found to segregate with childhood absence epilepsy (CAE) in some families; hence, GABRB3 was considered a Mendelian gene for CAE." (PMID 25025424, 2014). "Regarding the modulators of GABAergic transmission, the major FS hubs are GABRB3, a gene coding a GABAA receptor subunit and in which mutations are known to cause childhood absence epilepsy, and SLC32A1, that codes for a vesicular GABA transporter." (PMID 22022585, 2011).
Cognitive impairment (5 papers, 2012 to 2023). Abnormal cognition is characterized by deficits in thinking, reasoning, or remembering. "Gabrb3+/N328D mice showed spontaneous seizures and signs of cognitive impairment, including deficits in spatial learning, memory, and locomotion." (PMID 37176165, 2023). "The strategy that Gabrb3+/N328D mice used to find the target hole also significantly differed from WT mice and indicated a cognitive impairment." (PMID 37176165, 2023). "However, the inhibition of Gabrb3 and Cav1.2 alleviated cognitive impairment and reduced neurotoxicity." (PMID 36176629, 2022). "To explore whether GABRB3 plays a role in sevoflurane-induced cognitive impairment in neonatal mice, we injected bicuculline (a GABRB3 inhibitor) subcutaneously before sevoflurane exposure." (PMID 36176629, 2022). "Our Gabrb3ECKO mouse model highlights that deletion of Gabrb3 from blood vessels is sufficient to mimic a range of symptoms, such as hyperactivity and sensorimotor gating deficits; negative symptoms such as abnormal home cage behavior, impaired sociability, as well as cognitive impairments." (PMID 35318369, 2022). "In 2–4-month-old male and female C57BL/J6 wild-type and Gabrb3+/N328D mice, we investigated seizure severity using video-monitored EEG, cognitive impairment using a suite of behavioral tests, and profiled GABAAR subunit expression by Western blot." (PMID 37176165, 2023).
Dravet syndrome (5 papers, 2012 to 2022). "Our study explores a likely new gene‐phenotype relationship between a novel GABRB3 gene variant and the clinical manifestations of Dravet syndrome (DS)." (PMID 32945607, 2020). "Mutations in GABRs, especially in GABRA1, GABRB2, GABRB3, and GABRG2, impair GABAergic signaling and are frequently associated with DEEs such as Dravet syndrome and Lennox–Gastaut syndrome, as GABAergic signaling is critical for early brain development." (PMID 36077081, 2022). "Recently, GABAA receptor subunit genes (GABRs) encoding α1 (GABRA1), β3 (GABRB3) and γ2 (GABRG2), but not β2 (GABRB2) or β1 (GABRB1), subunits are frequently associated with Dravet syndrome or Dravet syndrome-like phenotype." (PMID 34095830, 2021).
infantile spasms (5 papers, 2016 to 2025). A rare epilepsy syndrome characterized by onset of epileptic spasms in infants between 2 and 12 months of age, and rarely up to 24 months. "Recently, GABRB3 mutations have been identified in a few patients with infantile spasms and Lennox–Gastaut syndrome." (PMID 26645412, 2016). "In particular, the GABRB3(D120N) and GABRB3(N110D) mutations have been identified in patients with LGS and infantile spasms, respectively." (PMID 37176165, 2023). "Similar tonic seizures have been observed in both Gabrb3+/D120N and Gabrb3+/N110D mouse models associated with LGS and infantile spasms, respectively." (PMID 37176165, 2023). "Several mutations in GABRB3, which encodes the GABAAR β3 subunit, are implicated in LGS, childhood absence epilepsy, and infantile spasms, an infantile epilepsy that often progresses to LGS." (PMID 37176165, 2023). "Gabrb3+/N110D and Gabrb3+/D120N knock-in mouse models exhibit many features of LGS and infantile spasms." (PMID 37176165, 2023).
juvenile myoclonic epilepsy (5 papers, 2012 to 2023). "Previous studies have shown that mutations of the GABA receptors, such as, GABRA1, GABRA5, GABRA6, GABRB3, GABRD, GABRG2, were associated with idiopathic generalized epilepsy." (PMID 35663265, 2022).
absence seizures (4 papers, 2016 to 2023). "There was a thorough comparison of the GABRB3 (N328D) mutation associated with LGS with GABRB3 (E357K), a mutation associated with a less severe phenotype: juvenile absence epilepsy." (PMID 36077081, 2022). "A decrease in thalamic β3 subunit expression in Gabrb3+/N328D mice may contribute to decreased regional inhibition that underlies the pathophysiology of atypical absence seizures." (PMID 37176165, 2023). "Gabrb3+/N328D mice exhibited spontaneous tonic and atypical absence seizures, which are two primary seizure types observed in children affected with LGS." (PMID 37176165, 2023). "Finally, it is noteworthy that patients with GABRB3 protein-truncating variants tend to have less severe outcomes than those with missense LOF variants, with absence seizures and frequent familial inheritance." (PMID 35383156, 2022).
alcoholism (4 papers, 2012 to 2021). "Song and colleagues reported that paternal transmission of GABRB3 was associated with alcoholism." (PMID 25025424, 2014). "Several previous studies reported that GABRB3 was associated with alcoholism." (PMID 25025424, 2014). "A significant association between alcohol dependence and the GABAA receptor genes GABRB3 and GABRA5 was also revealed in a family-based association study in the Caucasian population." (PMID 34530807, 2021). "The top candidate genes that we identified include genes which have previously been associated with alcoholism, such as Gabrg2, Gabrb3 and Gria3, but also genes that have not been associated with alcoholism before." (PMID 22629472, 2012).
breast carcinoma (4 papers, 2015 to 2025). "The second homozygous region on chromosome 15 (ROH4) hosts two genes of the gamma-aminobutyric acid A receptor family (GABRB3 and GABRB5), that are related to the chemokinesis and chemotaxis in MDA-MB-468 human breast carcinoma cells." (PMID 26558712, 2015).
developmental delay (4 papers, 2016 to 2025). "Recent studies confirm that duplications in this region, involving genes such as SNRPN, UBE3A, and GABRB3, are associated with neuronal hyperexcitability and synaptic alterations, resulting in autistic phenotypes with seizures and developmental delay." (PMID 40943430, 2025).
Asperger syndrome (3 papers, 2013 to 2024). "Studies demonstrated that variants in the GABRB3 gene are significantly associated with Asperger syndrome, a subtype of ASD." (PMID 39202440, 2024). "Warrier and colleagues examined the association between 45 SNPs in GABRB3 and Asperger syndrome; they found significant association of three SNPs with Asperger syndrome and multiple related endophenotypes of ASD." (PMID 24999380, 2014).
cleft palate (3 papers, 2010). Cleft palate is a fissure type embryopathy that affects the soft and hard palate to varying degrees. "Because it was reported previously that a homozygous null mutation of Gabrb3 caused cleft palate, we also generated mice with single homozygous Gabrb3 mutation for the purpose of comparison." (PMID 20808828, 2010). "The most prominent phenotype noted by us and other investigators has been the surprising presence of a cleft palate in neonatal mice homozygous for null mutations in Gad1, Viaat and Gabrb3." (PMID 20333300, 2010). "Inactivation of Gabrb3 in mice led to the development of cleft palate in a proportion of the homozygous offspring." (PMID 20333300, 2010). "Concerning the mechanism of onset of cleft palate, studies using knockout mice have revealed associations between cleft palate and mutation of genes related to GABA signaling, such as GAD67 and GABRB3." (PMID 21190592, 2010).
cognitive decline (3 papers, 2023 to 2025). "An outstanding question remains as to how regional disruption contributes to the pathophysiology of seizures and cognitive decline of Gabrb3+/N328D mice." (PMID 37176165, 2023). "We found that the Gabrb3+/N328D mouse recapitulates the major hallmarks of LGS, including major seizure types and EEG activity patterns characteristic of LGS patients as well as a deficit in locomotion and learning and memory capabilities, indicating cognitive decline." (PMID 37176165, 2023).
glioma (3 papers, 2009 to 2024). A benign or malignant brain and spinal cord tumor that arises from glial cells (astrocytes, oligodendrocytes, ependymal cells). "Higher GABRB3 expression levels were significantly associated with OS in all glioma subtypes, namely astrocytoma, oligoastrocytoma, and oligodendroglioma (Bonferroni-adjusted p < 0.05)." (PMID 38539663, 2024). "In patients with lower grade gliomas, GABRA3, GABRB3, GABRG1, and GABRG2, were associated with longer OS." (PMID 38539663, 2024). "We previously reported that high levels of GABRA2, GABRA3, GABRB3, GABRG1, and GABRG2 indicated better prognosis in glioma, and GABRB3 was particularly associated with longer OS in patients with lower-grade gliomas." (PMID 39595908, 2024). "High GABRB3 expression was related to longer survival when low grade glioma types were analyzed separately." (PMID 38539663, 2024).
idiopathic generalized epilepsy (3 papers, 2021 to 2023). A generalised epilepsy that encompasses several common seizure phenotypes including childhood absence epilepsy, juvenile absence epilepsy, juvenile myoclonic epilepsy and epilepsy with generalized tonic-clonic seizures alone. "There are also variants in GABRA1, GABRB3 or GABRG2 that are all associated with GGEs ranging from CAE, generalized epilepsy with febrile seizures plus (GEFS+), myoclonic atonic epilepsy (MAE) to other developmental EEs." (PMID 34095830, 2021).
colon adenocarcinoma (2 papers, 2022 to 2024). "For example, the expression of GABRB2 and GABRB3 is associated with colon adenocarcinoma occurrence, and a low expression of GABRB1 correlates with patient survival in that cancer type." (PMID 39595908, 2024). "Ling Yan and colleagues showed that overexpression of GABRA2, GABRA3, GABRB3, GABRG2, GABRG3, GABRD, and GABRE might be diagnostic for colon adenocarcinoma." (PMID 35565356, 2022).
depression (2 papers, 2013 to 2025). "Six potential depression‐related target genes of miR‐511‐3p were identified: CXCR4, LBR, CPS1, VPS13B, COL9A3, and GABRB3." (PMID 41341504, 2025). "Additional examples include schizophrenia for RELN, GluR6, GRIN2A, GRIN2B, and CNTNAP2, childhood absence epilepsy for GABRB3, ADHD and depression for 5-HTT, and major depression for TPH2." (PMID 23935565, 2013).
Hypertension (2 papers, 2021 to 2022). The presence of chronic increased pressure in the systemic arterial system. "Of these genes, A2ML1, AGGF1, CBS, ECE1, GABRB3, GALNT2, MRPS6/SLC5A3, and SPG7 had documented associations with hypertension, ischemic stroke and methionine metabolism, atherosclerosis, and early-onset MI." (PMID 34252155, 2021). "That elimination of vascular Gabrb3 can contribute to abnormal blood flow in the brain with downstream impairment in several behavioral domains, as well as hypertension emphasizes a novel concept that bridges a major gap between vascular biology and psychiatry." (PMID 35318369, 2022). "Additionally, the Gabrb3ECKO mice developed hypertension, suggesting that vascular Gabrb3 plays major roles in both the brain and the heart, and its loss in both organs may contribute to concurrent development of psychiatric illness and heart disease." (PMID 35318369, 2022).
Lennox-Gastaut Syndrom (2 papers, 2022). "A woman with Lennox-Gastaut syndrome (LGS) from a disease-causing variant in GABRB3 experienced a sustained, dose-dependent decrease in epileptiform activity on EEG after starting vinpocetine, a synthetic derivative of vincamine which is an alkaloid derived from the periwinkle plant." (PMID 35250833, 2022).
neuroblastoma (2 papers, 2019 to 2024). Neuroblastoma (NB) is the most common solid, extracranial childhood tumor. "The upregulation of genes BSG/CD147, CCDC125, GABRB3, GNB2L1/RACK1, HAPLN4, HEBP2, and HSD17B12 is associated with poor neuroblastoma prognosis and low EFS." (PMID 38398114, 2024). "A set of six markers (CCND1, DDC, GABRB3, ISL1, KIF1A, PHOX2B) was identified by genome-wide gene expression microarray analyses of 48 neuroblastoma tumors and nine remission BM samples followed by selecting genes with higher tumor-to-BM expression ratios." (PMID 31214500, 2019).
benign adult familial myoclonus epilepsy (1 paper, 2023). "The first reported linkage study of FAME (or benign adult familial myoclonus epilepsy) targeted the gene for dentatorubral pallidoluysian atrophy (DRPLA), in which a causative CAG repeat expansion had been discovered, and the GABRB1, GABRB3, and GABRB6 genes." (PMID 37021642, 2023).
brain malformations (1 paper, 2021). "The ratio was highest in 6 (85.7%) of the 7 patients with genetic seizures (6 are KCNQ2 seizures, 1 is GABRB3); 15 (36.6%) of the 41 cases of HIE; 3 (30%) of the 10 cases with congenital structural brain malformations; 4 (57.1%) of the 7 hypocalcemic or hypoglycemic seizures." (PMID 34414144, 2021).
channelopathy (1 paper, 2015). Channelopathies are a group of diseases caused by the dysfunction of ion channel subunits or their interacting proteins. "Recent gene discoveries such as GABRB3, GRIN2A, HCN1, KCNA2, and KCNH1 support the channelopathy hypothesis, and genes that encode ion channels certainly represent the largest class of disease-causing genes in epilepsy." (PMID 26302787, 2015).
cholangiocarcinoma (1 paper, 2018). A carcinoma that arises from the intrahepatic biliary tree (intrahepatic cholangiocarcinoma) or from the junction, or adjacent to the junction, of the right and left hepatic ducts (hilar cholangiocarcinoma). "We obtained in vivo evidence for deregulation of this tumor suppressive mechanism in human cholangiocarcinomas, where several genes involved in taurine-mediated volume regulation (GABRB3, PANK1 and LRRC8a) were repressed." (PMID 29787571, 2018). "To correlate taurine signaling and proliferation, we determined GABRB3, GABRA5 and Ki67 protein levels in 7 cholangiocarcinoma samples by immunohistochemical staining (IHC)." (PMID 29787571, 2018). "In all samples GABRB3 was reduced or completely lost in tumor cells, whereas GABRA5 protein was reduced in part of the neoplastic ductular structures in 3 out of 7 cholangiocarcinoma samples." (PMID 29787571, 2018). "Microarray-based expression profiling of 104 resected human cholangiocarcinomas revealed reduced expression of GABRB3, PANK1, and LRRC8A, but not GABRA5 or ADO, compared to micro-dissected bile duct controls." (PMID 29787571, 2018). "Stratifying the cohort of 104 cholangiocarcinomas for RNA expression above and below the mean revealed that low RNA expression of GABRA5, LRRC8a, ADO and PANK1, but not GABRB3, was associated with reduction of the median survival time of patients by 1.8, 2.1, 3.3, and 4.3 years, respectively." (PMID 29787571, 2018).
colon cancer (1 paper, 2024). "Gene expression of GABRB3, GABRG2, and GAD1 positively correlated with genes involved in the synthesis of PGE2 (PTGS2 and PTGES) as well as IL‐6 in human colon cancer." (PMID 38886975, 2024).
dementia (1 paper, 2021). Loss of intellectual abilities interfering with an individual's social and occupational functions. "Several of these have been associated with other neurodegenerative disorders (ZDHHC17 with Huntington’s disease, SYT11 and GAK with Parkinson’s disease and GABRB3 with dementia with Lewy bodies), and may be of special interest for future studies." (PMID 34202490, 2021).
Down syndrome (1 paper, 2023). "Six cases (31.58%) had an unknown etiology, and four cases (21.05%) had genetic etiology (one each with methylmalonic acidemia, Down syndrome, maternal heterozygous GABRB3 variation, and de novo heterozygous IRF2BP variation)." (PMID 37928352, 2023).
early infantile epileptic encephalopathy (1 paper, 2024). "Mutation of GABRB3 has been previously linked to human early infantile epileptic encephalopathy." (PMID 39534499, 2024).
esophageal cancer (1 paper, 2025). A primary or metastatic malignant neoplasm involving the esophagus. "However, the exact mechanisms by which MAPK12, CHAF1B, and GABRB3 are involved in the progression of esophageal cancer have not yet been reported in the literature and warrant further exploration." (PMID 41473739, 2025).
generalized seizure (1 paper, 2016). "The same two‐locus model of GABRB3_rs878960‐SCN1A_rs1813502 of ion channels and their functionally related genes was, however, also observed in generalized seizure patients but with low CVC value of 6/10." (PMID 27458546, 2016).
heart failure (1 paper, 2022). Inability of the heart to pump blood at an adequate rate to meet tissue metabolic requirements. "It will also be interesting to examine the long-term effects of loss of vascular Gabrb3-GABA signaling in cardiac tissue, and to evaluate whether this can lead up to heart failure with aging." (PMID 35318369, 2022).